SOX2 (SRY-box transcription factor 2)
Diseases named in the same sentence as SOX2 in open-access papers (continued):
Sharing a sentence is not in itself a finding about the gene and the disease.
gastric cancer (continued). "Conversely, Anti-miR-126 transfection up-regulated the SOX2 protein levels in both the HSC43 and NUGC3 cell lines, indicating that not only exogenous Pre-miR-126 but also endogenous miR-126 can regulate SOX2 protein levels in gastric cancer cells." (PMID 21304604, 2011). "To further compare the expression pattern of miR-126 with that of SOX2 in primary gastric cancers, we initially examined the expression levels of SOX2 protein in 15 primary gastric cancer tissue samples without DNA methylation of SOX2 by immunohistochemistry." (PMID 21304604, 2011). "SOX2 hypermethylation signals were observed in some cultured and primary gastric cancers with no or weak SOX2 expression." (PMID 18268498, 2008). "Altogether, 12 out of 74 (16.2%) primary gastric carcinoma tissues exhibited the hypermethylation signals of SOX2, whereas none of the 24 corresponding noncancerous tissues did (Fisher's exact probability test, P=0.027)." (PMID 18268498, 2008). "Mechanistically, KMT2A activated the translocation of β-catenin into the nucleus of gastric cancer cells, and then, β-catenin served as a coactivator of KLF11, which promoted the expression of specific gastric cancer stemness-related molecules, including SOX2 and FOXM1." (PMID 38025523, 2023). "However, the relationship between SOX2 expression and lapatinib resistance in HER2-positive gastric cancer cells remains unclear." (PMID 38012281, 2023). "Therefore, the role of Sox2 and ALDH1A1 in gastric cancer remains nebulous." (PMID 28046028, 2017). "Moreover, we also compared gastric cancer stem cells marker expression, such as OCT-4, Sox2, Nanog, Survivin and CD44, in tumor spheres and tumor spheres treated with ICG-001, which showed those markers were higher in tumor spheres than cell lines, but declined after ICG-001 treatment." (PMID 28893318, 2017). "However, there have been no reports on miRNA(s) that can regulate SOX2 expression in human gastric cancer." (PMID 21304604, 2011). "Furthermore, the SOX2 hypermethylation was more frequently observed in primary gastric carcinomas than corresponding noncancerous mucosae (16.2 vs 0%, respectively)." (PMID 18268498, 2008). "However, Sox2 expression status had no bearing on survival rates in in non-cardiac gastric cancers." (PMID 28046028, 2017). "In our study, we found that Sox2 was associated with lymphnode metastasis in gastric cardiac cancer (Siewert type II and III); however, the exact mechanism by which Sox2 correlated with poor survival in cardiac gastric cancer but not with non-cardiac gastric cancer needs further research." (PMID 28046028, 2017). "In our study, the expression of transcription factors Oct4, Sox2, c-MYC, Nanog and SALL4 as well as the ability to differentiate into adipocytes in gastric cancer cells were enhanced by low level of DIM, suggesting that low level of DIM may affect gastric cancer cell reprogramming." (PMID 26918831, 2016). "This phenomenon is particularly relevant in cancers exhibiting microsatellite instability (MSI), such as MSI-high gastric cancers and CRCs; however, no clinical data have yet established a direct relationship among ACSS2, MSI-high tumors, and Sox2 expression." (PMID 38473392, 2024). "By contrast, other studies have shown a correlation between high SOX2 expression and negative lymph node status in HNSCC patients, as well as a favorable prognosis in NSCLC, gastric cancer and HNSCC patients." (PMID 28002801, 2017). "Two SOX2 expression-negative gastric cancer cell lines (MKN74 and HSC59) exhibited the hypermethylation signals by MSP and bisulphite sequencing, and restored the SOX2 expression after the demethylating agent treatment." (PMID 18268498, 2008).
ovarian carcinoma (121 papers, 2013 to 2026). A malignant neoplasm originating from the surface ovarian epithelium. "SOX2 expression can be detected in 10–60.5% of ovarian carcinomas and has been associated with poor clinical outcome." (PMID 35162954, 2022). "Increased expression of SOX2 has been associated with poor prognosis and a higher grade of ovarian cancer." (PMID 36551731, 2022). "Though having no influence on proliferation or apoptosis, cocultured UC-MSCs greatly enhance SP ratio in both breast and ovarian cancer cells, as well as upregulating the well-characterized tumor-associated pluripotency factors Sox2 and Oct4." (PMID 29670904, 2018). "A recent report showed that SOX2 expression was associated with stem cell state in human ovarian carcinoma." (PMID 26654944, 2016). "While an association between Sox2 and ST6Gal-I mRNA levels has been noted previously, results herein show that Sox2 and ST6Gal-I expression at the protein level is correlated across multiple ovarian cancer cell lines." (PMID 31610800, 2019). "In addition, tumour xenografts derived from Oct4A knockdown cells displayed relatively lower abundance of markers associated with ovarian cancer including oncogenic markers Lin28 and Sox2, along with proliferation maker Ki67 and anti-apoptotic Bcl-2 expression." (PMID 26260289, 2015). "The results demonstrated that treatment with 10 μM Ivosidenib reduced the expression of ALDH1A1 and SOX2 in ovarian cancer cells compared to the DMSO control group." (PMID 40342735, 2025). "In a study, crocin with cisplatin exhibited cytotoxic effects on ovarian cancer cells by inhibiting the expression of the SOX2 gene." (PMID 39055876, 2024). "We found that ovarian cancer cells treated with carboplatin in combination with CCL2/MCP-1 for 48 hours had increased SOX2, OCT4, and NANOG gene expression and greater spheroid formation ability relative to carboplatin or CCL2/MCP-1 treatment alone." (PMID 39287565, 2024). "A mechanism for upregulated ST6Gal-I expression in ovarian cancer has recently been suggested whereby SOX2 and ST6GAL1 are coordinately amplified in cancer cells, with the Sox2 protein then binding the ST6GAL1 promoter to further augment ST6Gal-I expression." (PMID 38515194, 2024). "LSD1 is a selective epigenetic target in SOX2-expressing cancer treatment, particularly in SOX2-rich carcinomas associated with small cell lung cancer (SCLC), ovarian cancer, and cervical cancer." (PMID 36810560, 2023). "The overexpression of SOX2, which is a CSC-associated gene, stimulated cell proliferation, migration, resistance to cisplatin treatment, and the tumorigenicity of ovarian cancer cells." (PMID 38201468, 2023). "The Cancer Genome Atlas (TCGA) database analysis showed that the alteration frequency of SOX2 in ovarian cancer was the second strongest among all carcinomas." (PMID 37596406, 2023). "In regard to ovarian cancer, various specific markers of stemness, such as Nanog, SOX2, and OCT4, have been used to isolate and characterize ovarian cancer stem cells." (PMID 36625999, 2023). "In ovarian cancer SOX2 ectopic overexpression promotes tumor cell resistance to several chemotherapeutic compounds, such as cisplatin, carboplatin, and paclitaxel, by altering the homeostasis between pro- and anti-apoptotic proteins." (PMID 38096163, 2023). "A model that estimates the likelihood of ovarian cancer with the best association with outcomes was developed with nine proteins (P38MAPK, RAB11, FOXO3A, AR, BETACATENIN, Sox2, IGFRb, AKT_pS473, and ERCC5) using a LASSO–Cox algorithm." (PMID 37189432, 2023). "The results showed that HMGB3 knockdown significantly impairs the spheroid forming ability of ovarian cancer cells and inhibits SOX2 and ALDH1A1 expression." (PMID 37328851, 2023). "Previous studies have shown that SOX2 enhances the migration and invasion of laryngeal cancer cells and ovarian cancer cells through the upregulation of MMP2 expression." (PMID 36293387, 2022).
ovarian carcinoma (continued). "Elevated SOX2 gene expression has been identified in ovarian cancer cell lines and patient tissue samples." (PMID 36551731, 2022). "Few studies have critically investigated the role SOX2 plays in ovarian cancer and its relation to tumor-initiating cells." (PMID 36551731, 2022). "Knockdown of SOX2 not only decreased the formation of spheroids, but also reduced the expression of other stemness-related genes and resensitized ovarian cancer spheroids to cisplatin treatment." (PMID 36551731, 2022). "PIK3R3 expression in ovarian cancer positively correlated with sex determining region Y-box 2 (SOX2), CD44, and aldehyde dehydrogenase 1 (ALDH1A1)." (PMID 35761259, 2022). "Altogether, our findings suggest that SOX2 should be considered when evaluating ovarian cancer TIC populations and relapse potential." (PMID 33445692, 2021). "SOX2 expression is upregulated in several types of CSCs, including those of breast, gastric, lung, and ovarian cancers." (PMID 34064635, 2021). "Future studies evaluating SOX2 in TIC biology will increase our understanding of the mechanisms that drive ovarian cancer relapse." (PMID 33445692, 2021). "CD117+ ovarian cancer cells overexpress SOX2, octamer-binding transcription factor 4 (OCT4), and NANOG, which are CSC markers involved in stemness and chemoresistance." (PMID 34064635, 2021). "The expression of SOX2 correlates with poor prognosis for stage I lung adenocarcinoma, squamous cell carcinoma, gastric carcinoma, small cell lung cancer, and ovarian carcinoma." (PMID 35008527, 2021). "It has been shown that DFO downregulates the expression of cancer stem cell markers, including SOX2, Nanog, and c-Myc in two ovarian cancer cell lines (SKOV-3 and OVCAR-3)." (PMID 35008527, 2021). "Following sequential carboplatin treatment of 2D cultured ovarian cancer cell lines, only SOX2 expression remained elevated after the third treatment, suggesting a role for SOX2 in platinum resistance." (PMID 34283069, 2021). "Furthermore, SOX2 is overexpressed and associated with poor prognosis in almost all human cancer types; it is considered to be a key regulator of tumorigenicity, drug resistance, and metastasis in a variety of tumors, including cancers of the ovary, lung, skin, brain, breast, prostate, and pancreas." (PMID 34809669, 2021). "Similar to OCT4 and SOX2, c-Myc has characteristics of stemness and pluripotency, and is overexpressed not only in ovarian cancer but also in most types of malignant tumors." (PMID 35582216, 2020). "We analysed the effect of tumour environment on the expression of NANOG/OCT4/SOX2, three core pluripotency factors in human ovarian cancer cells." (PMID 32329191, 2020). "PD-L1 was also shown to enhance tumor sphere formation of ovarian cancer cells possibly by increasing SOX2 expression." (PMID 33363153, 2020). "Detailed analysis of ovarian cancer spheroids revealed the mutual regulatory pathway of ALDH1 and Sox2 involved in ovarian cancer stem cells." (PMID 31939100, 2020). "The SOX2+ SOCs contributed to therapy resistance to staurosporine, carboplatin, cisplatin and paclitaxel and disease relapse in the patients with ovarian cancer through induction of cancer stemness and apoptosis resistance." (PMID 30517668, 2020). "To this end we employed RT-qPCR analysis, western blot and/or immunofluorescence to assess the expression of CD44, NANOG, OCT4 and SOX2, regarded as putative ovarian cancer stem cells markers." (PMID 33250051, 2020). "In the aggregate, these data suggest that Sox2 directly promotes the expression of ST6Gal-I in ovarian cancer cells, leading to enhanced surface α2–6 sialylation." (PMID 31610800, 2019). "Autotaxin is upregulated in many cancers, and is regulated via OCT4, SOX2, and Nanog; an association between ATX and ALDH1 has also been observed in ovarian cancer tumorigenic sphere cells." (PMID 31661927, 2019).
ovarian carcinoma (continued). "Like ST6Gal-I, Sox2 is upregulated in ovarian cancer, and its expression is particularly enriched in the CSC population of many different malignancies." (PMID 31610800, 2019). "The current study adds to the body of literature by highlighting a novel role for Sox2 in promoting expression of ST6Gal-I in ovarian cancer cells." (PMID 31610800, 2019). "To substantiate a role for Sox2 in regulating ST6Gal-I expression, we modulated Sox2 expression in ovarian cancer cells, and then measured ST6Gal-I mRNA and protein." (PMID 31610800, 2019). "We also compared Sox2 and ST6Gal-I expression in the matched, isogenic chemosensitive/chemoresistant A2780 ovarian cancer cell series, specifically, the A2780-IP2 line, which is sensitive to cisplatin, and the A2780-CP20 line, which is cisplatin-resistant." (PMID 31610800, 2019). "A similar correspondence in Sox2 and ST6Gal-I protein levels was observed in additional ovarian cancer cell lines." (PMID 31610800, 2019). "The OVCAR4 line is one of the few ovarian cancer lines that lacks detectable ST6Gal-I protein (unpublished observation), and Sox2 is likewise undetectable in this line." (PMID 31610800, 2019). "Of note, 3q26 amplification is an early event in tumorigenesis, which aligns with evidence suggesting that Sox2 functions as an initiating oncogene in ovarian cancer." (PMID 31610800, 2019). "Sox2 serves as a pivotal regulator to confer certain stem cell properties to ovarian cancer cells to allow them to grow, differentiate and survive." (PMID 30064416, 2018). "Recent studies have shown that RAD6, an ubiquitin-conjugating enzyme originally identified as a DNA repair protein, plays a key role in the induction of SOX2 expression in ovarian cancer cells and in the maintenance of a cancer stem cell phenotype." (PMID 29389895, 2018). "SOX2 expression in ovarian cancer cells is induced by a regulatory pathway involving hypoxia-mediated NOTCH1 activation." (PMID 29389895, 2018). "Overexpression of NANOG, SOX2 and OCT4 have been linked to therapy resistance, reduced overall survival and increased progression in ovarian cancer, head and neck, breast, renal and rectal cancer patients." (PMID 30513961, 2018). "In the case of ovarian cancer, both the percent of SOX2-positive tumors and the percent of SOX2-positive cells within these tumors have been reported." (PMID 28388544, 2017). "Next, to identify the molecular mechanism of KDM3A-mediated ovarian cancer stemness, we assessed the expression of stem cell pluripotent markers such as Sox2, Oct4, Nanog and Lin28 by real-time RT-PCR." (PMID 27694900, 2017). "Static cultures produced unusual staining for both markers, however only perfused culture demonstrated high levels of nuclear Nanog, as observed for SOX2+ve population in Neuroblastoma and Ovarian cancer cells." (PMID 28842598, 2017). "KDM3A and Sox2 expressions were significantly elevated in ovarian cancer than the adjacent normal tissues." (PMID 27694900, 2017). "Disappointingly, for some cancers, in particular head and neck squamous cell carcinomas and ovarian cancer, there are conflicting reports regarding the levels of SOX2 expression and patient survival." (PMID 28388544, 2017). "Here we identified that lysine demethylase KDM3A as a critical regulator of ovarian cancer stemness and cisplatin resistance by inducing the expressions of pluripotent molecules Sox2 and Nanog and anti-apoptotic B-cell lymphoma 2 (Bcl-2), respectively." (PMID 27694900, 2017). "In summary, in this study we demonstrated that SOX2 overexpression occurs in a fraction of women with BRCA1 and BRCA2 mutations prior to ovarian cancer initiation and in the majority of patients with HGSOCs irrespective of tumor stage." (PMID 27492892, 2016). "The pluripotency associated stem cell factors SOX2 (sry related) and LIN-28 have been found to be expressed in ovarian cancer cell lines and tissue." (PMID 27049920, 2016).
ovarian carcinoma (continued). "In ovarian cancer patients receiving taxanes, expression of SOX-2 was shown to be correlated with chemotherapy resistance and a shorter PFS whereas patients receiving non-taxane based chemotherapy showed no significant response influence." (PMID 27049920, 2016). "Accumulating data have shown elevated expression of SOX2 in several types of CSCs, including breast, gastric, lung, and ovarian cancer." (PMID 27489349, 2016). "In this work we demonstrated that pre-cancer SOX2 overexpression in the FTE is nearly ubiquitous in HGSOCs and is also a common feature in women with BRCA1 and BRCA2 mutations prior to ovarian cancer initiation." (PMID 27492892, 2016). "Knockdown of SOX2 expression with shRNA in primary ovarian cancer spheres resulted in significantly decreased sphere forming activity and ABCG2 expression." (PMID 27489349, 2016). "Hypoxic treatment or overexpression of intracellular domain of NOTCH1 (NICD1) in ovarian cancer cells increased sphere formation, drug resistance, and expression of CSC-associated genes such as SOX2, ALDH, and ABC transporters." (PMID 27489349, 2016). "In the current study, we showed FOXP1 up-regulated transcription activity of ABCG2, OCT4, NANOG, and SOX2 in A2780 ovarian cancer cells." (PMID 26654944, 2016). "In the present study, we identified SOX2 as a key transcription factor for CSC-like characteristics in the downstream of hypoxia-induced NOTCH signaling in epithelial ovarian cancer cells." (PMID 27489349, 2016). "Our results for nuclear Survivin and cytoplasmic Survivin at the protein level in ovarian cancer tissues indicated that nuclear Survivin expression was consist with Sox2 expression." (PMID 26198101, 2015). "In line, SOX2 knockdown reduces sphere formation and in vivo tumorigenicity in breast as well as ovarian carcinoma cells." (PMID 26498353, 2015). "We observed that ovarian cancer spheroids originating from ES-2 cells, which overexpressed Sox-2 and N-cadherin, had high Btk pathway activation." (PMID 26036311, 2015). "Recently, it has been shown that SOX2, a gene encoding a transcription factor that targets FN1, is a key gene regulating cell migration in ovarian cancer." (PMID 24676469, 2014). "And we found that SOX2 was expressed in an SP/ALDHBr population at higher level, and gene knockdown of SOX2 abrogated the tumor-initiation of ovarian cancer cells." (PMID 23967051, 2013). "However, in ovarian cancer cell lines, SOX2 is a contextual and contrastingly regulated signaling node downstream of TGF-β." (PMID 41189680, 2026). "The knockdown of the CD90 molecule in A2780 (ovarian cancer) cells decreased the proliferative activity of cells, relative cell growth (self-renewal potential), and expression of the pluripotency-related markers Nanog and Sox2." (PMID 38791431, 2024). "We have previously shown that SOX2 is a marker of chemoresistance and recurrence in ovarian cancer; thus, we next sought to characterize changes in SOX2, OCT4, and NANOG expression in ovarian cancer cells indirectly co-cultured with differentially polarized macrophage populations." (PMID 39287565, 2024). "Furthermore, recent research has highlighted SOX2 as a consistent marker for tumor‐initiating cells (TICs) in ovarian cancer contributing to relapse and resistance to chemotherapy." (PMID 38400679, 2024). "There is considerable evidence to suggest that Sox2 is critical for maintaining ovarian cancer stem cell pluripotency as well as determining stem cell fate, and targeting Sox2 may be therapeutically beneficial." (PMID 37189432, 2023).